TIGAR (TP53 induced glycolysis regulatory phosphatase)
Description:
Fructose-bisphosphatase hydrolyzing fructose-2,6-bisphosphate as well as fructose-1,6-bisphosphate. Contributes to the generation of reduced glutathione to cause a decrease in intracellular reactive oxygen species (ROS) content, correlating with its ability to protect cells from oxidative or metabolic stress-induced cell death. Plays a role in promoting protection against cell death during hypoxia by decreasing mitochondria ROS levels in a HK2-dependent manner through a mechanism that is independent of its fructose-bisphosphatase activity. Reduced mitophagy results in an enhanced apoptotic myocyte cell death, and exacerbates cardiac damage (By similarity). Plays a role in adult intestinal regeneration; contributes to the growth, proliferation and survival of intestinal crypts following tissue ablation. Plays a neuroprotective role against ischemic brain damage by enhancing PPP flux and preserving mitochondria functions (By similarity). Plays a role in cancer cell survival by promoting DNA repair through activating PPP flux in a CDK5-ATM-dependent signaling pathway during hypoxia and/or genome stress-induced DNA damage responses. Involved in intestinal tumor progression.
Synonyms: C12orf5; FR2BP
Tractability: PROTAC: ubiquitination databases record sites on it; its protein half-life has been measured.
Target class: Enzyme; Hydrolase
Gene: Protein-coding gene on chromosome 12 (4,307,763 to 4,360,028, forward strand). Ensembl gene ENSG00000078237.
Subcellular location: Cytoplasm; Nucleus; Mitochondrion
Subcellular location (Human Protein Atlas): Cytosol
Gene Ontology:
Molecular function: fructose-2,6-bisphosphate 2-phosphatase activity; protein binding; catalytic activity
Biological process: cellular response to cobalt ion; cellular response to hypoxia; DNA damage response; negative regulation of programmed cell death; positive regulation of DNA repair; positive regulation of hexokinase activity; regulation of pentose-phosphate shunt; regulation of response to DNA damage checkpoint signaling; negative regulation of glycolytic process; response to ischemia; positive regulation of pentose-phosphate shunt; regulation of programmed cell death; response to stress
Cellular component: cytoplasm; cytosol; mitochondrial outer membrane; mitochondrion; nucleus
Genetic constraint (gnomAD): Loss-of-function variants: 4 observed, 7.65 expected, observed/expected ratio (o/e) 0.52, 90% interval 0.26 to 1.19. That is too few expected variants to judge how well the gene tolerates losing a copy. Missense variants: 218 observed, 292.65 expected, observed/expected ratio (o/e) 0.74, 90% interval 0.67 to 0.83. Synonymous variants: 87 observed, 102.72 expected, observed/expected ratio (o/e) 0.85, 90% interval 0.71 to 1.01.
Homologues: Orthologues: chimpanzee TIGAR (99% identical), macaque TIGAR (94% identical), dog TIGAR (84% identical), rabbit TIGAR (84% identical), pig TIGAR (80% identical), guinea pig TIGAR (79% identical), mouse Tigar (72% identical), rat Tigar (72% identical).
Diseases named in the same sentence as TIGAR in open-access papers:
TIGAR is named in the same sentence as 102 diseases in open-access papers, as found by Europe PMC text mining. Sharing a sentence is not in itself a finding about the gene and the disease. The quoted sentences say what the papers report.
breast carcinoma (19 papers, 2015 to 2025). "Analyzing TIGAR expression according to breast cancer subtypes, we found that TIGAR is increased in the FBP1-loss basal-like subtype of breast cancer." (PMID 32927665, 2020). "We provide important details to demonstrate that CRIF1 deletion-induced mitochondrial damage has an antitumor effect via TIGAR induction in BT549 breast cancer cells." (PMID 39682267, 2024). "A high expression of TIGAR is observed in the majority of breast cancers, where it contributes to tumor growth and metabolic changes in the tumor microenvironment." (PMID 39682267, 2024). "The TIGAR is highly expressed in a variety of solid tumors, such as lung cancer, colon cancer, breast cancer, and gastric cancer." (PMID 36979962, 2023). "TIGAR is strongly expressed in most breast carcinomas; this strong expression promotes tumor growth through enhanced generation of NADPH-derived ROS." (PMID 37108616, 2023). "In breast carcinoma cells, TIGAR overexpression leads to increased oxygen consumption and ATP production in parallel to enhanced levels of the translocase of the outer mitochondrial membrane 20 (TOM20)." (PMID 35163828, 2022). "More and more investigations have been conducted in this field, and they indicate high levels of TIGAR in hematopathy and solid tumors, including acute myeloid leukemia, lung cancer, colon cancer, pancreatic cancer and breast cancer." (PMID 35574353, 2022). "In a co-culture system, oxidative stress-induced autophagy correlated with caveolin-1 (CAV1) downregulation in CAFs and TIGAR overexpression in adjacent breast cancer cells." (PMID 30234009, 2018). "Furthermore, TIGAR is highly expressed in breast cancers and is localized to mitochondria, where it reduces NADPH production." (PMID 39682267, 2024). "Interestingly, when breast carcinoma cells overexpressing TIGAR were co-cultured with CAFs, these latter shifted versus a glycolytic phenotype." (PMID 34944758, 2021). "In addition, TIGAR overexpression has been shown to reprogram carcinoma and stromal cells in breast cancer, as well as to increase oxygen consumption rates and ATP levels in the presence of glutamine and lactate, leading to enhanced ATP synthesis." (PMID 30234009, 2018). "IHC staining of the CYGB-expressing tumors showed lower GLUT1 and HXK2 and higher TIGAR expression, substantiating that CYGB suppresses breast cancer through the regulation of these key glucose metabolism factors." (PMID 30545372, 2018). "In breast cancer, TIGAR overexpression allows malignant cells to increase mitochondrial metabolism by using extracellular lactate to fuel TCA, providing evidence for a role of TIGAR beyond glycolysis redirection and the PPP." (PMID 34299056, 2021). "TIGAR also showed high expression among several cancer types, including human colon tumors, breast cancer, and glioblastoma, which suggesting that upregulated TIGAR expression may support, rather than inhibit, cancer development." (PMID 27884166, 2016).
glioma (15 papers, 2014 to 2024). A benign or malignant brain and spinal cord tumor that arises from glial cells (astrocytes, oligodendrocytes, ependymal cells). "IDH1 mutations have been reported to radiosensitize glioma cells by epigenetic downregulation of TIGAR." (PMID 32899427, 2020). "In order to further demonstrate the mechanism of TIGAR knockdown-induced radiosensitization in TrxR1-overexpressing glioma cells, DNA damage-associated γ-H2AX foci and the cellular distribution of Trx1 were illustrated by immunofluorescence assay." (PMID 28338004, 2017). "TIGAR knockdown results in radiosensitization of U87 MG and T98G glioma cells, showing a senescent phenotype and a failure in DNA repair by ROS generation." (PMID 38786726, 2024). "This indicates that TIGAR is a major metabolic regulator, which can improve the survival rate of glioma cells under hypoxia." (PMID 36437984, 2022). "Glioma cells benefit from TIGAR expression through raising energy production of glucose and enhancing defense mechanism against ROS via increasing respiration." (PMID 36437984, 2022). "Knockout of TIGAR gene can radio-sensitize TrxR1-overexpressed gliomas through inhibiting the nuclear transport of IR-induced thioredoxin-1 (Trx1)." (PMID 36437984, 2022). "ROS sensitize glioma cells to chemotherapeutic agents, while TIGAR protects cells from ROS-related apoptosis." (PMID 36437984, 2022). "Knockout of TIGAR gene can radio-sensitize TrxR1-overexpressed gliomas through inhibiting the nuclear transport of IR-induced Trx1." (PMID 36437984, 2022). "Here, we established that LNT-229 glioma cell lines stably expressed shRNA constructs targeting TIGAR, and exposed them to hypoxia, irradiation and temozolomide." (PMID 30823646, 2019). "In an orthotopic mouse model using U87MG glioma cells, TIGAR knockdown prolonged the survival of tumor-bearing mice and enhanced the radiosensitivity of xenografts overexpressing thioredoxin reductase-1 (TRXR1)." (PMID 30823646, 2019). "In the glioma cell lines A172 and T98G, radiosensitization induced by siRNA-mediated TIGAR gene silencing correlated with an inhibition of thioredoxin-1 (TRX1) nuclear translocation." (PMID 30823646, 2019). "Using TrxR1-overexpressing xenograft models, it is revealed that TIGAR interfering is able to diminish the radioresistance, thus prolonging the survival time of nude mice bearing TrxR1-overexpressing gliomas notably." (PMID 28338004, 2017). "It was worth emphasizing that even in TrxR1-overexpressing glioma cells, IR-induced Trx1 nuclear transport was almost completely suppressed by TIGAR interfering." (PMID 28338004, 2017). "Predictably, TIGAR shRNA lentivirus transfection significantly reduced the size of TrxR1-overexpressing glioma, indicating an effective radiosensitization." (PMID 28338004, 2017). "In this study, the effects of TIGAR knockdown on TrxR1-overexpressing glioma cells were investigated." (PMID 28338004, 2017). "In conclusion, this study demonstrated the radiosensitizing effect of TIGAR silence on TrxR1-overexpressing glioma." (PMID 28338004, 2017). "Nevertheless, IR-induced Trx1 nuclear transport was apparently inhibited in TIGAR-low-expressing glioma cells." (PMID 28338004, 2017).
glioma (continued). "Our previous study has demonstrated that TIGAR knockdown significantly radiosensitizes A172 and T98G glioma cells by depleting NADPH and postponing the reducing process of Trx114." (PMID 28338004, 2017). "Immunofluorescence further demonstrated the mechanism of TIGAR silence-induced radiosensitization in TrxR1-overexpressing glioma cells." (PMID 28338004, 2017). "More importantly, the radiorensitivity of TrxR1-overexpressing glioma was dramatically enhanced by TIGAR interfering." (PMID 28338004, 2017). "When U-87MG glioma cells were treated with 8 Gy ionizing radiation, the ROS level was dramatically increased to 8 times by TIGAR knockdown." (PMID 28338004, 2017). "In order to confirm the mechanism of TIGAR abrogation-induced radiosensitization of TrxR1-overexpressing glioma in vivo, we carried out Trx1 transport assays on freshly harvested xenografts." (PMID 28338004, 2017). "Contrarily, TIGAR shRNA lentivirus transfection significantly prolonged the survival of animals suffered from TrxR1-overexpressing gliomas." (PMID 28338004, 2017). "TIGAR abrogation was able to radiosensitize TrxR1-overexpressing gliomas by inhibiting IR-induced Trx1 nuclear transport." (PMID 28338004, 2017). "In order to demonstrate the mechanism of TIGAR silence-induced radiosensitization in TrxR1-overexpressing glioma cells, IR-induced Trx1 nuclear translocation was examined." (PMID 28338004, 2017). "Nevertheless, the radioresistance of TrxR1-overexpressing U-87MG and T98G glioma cells was dramatically diminished by TIGAR interfering." (PMID 28338004, 2017). "Most noticeably, the clonogenic capacity of cells co-treated with TrxR1 overexpression and TIGAR abrogation was substantially lower than that of control cells, indicating a significant radiosensitization of TrxR1-overexpressing glioma cells." (PMID 28338004, 2017). "Glioblastoma have been found to show a high expression of TIGAR compared to normal brain tissue, and knockdown of TIGAR resulted in radiosensitisation in glioma cells through an accumulation of ROS, leading to DNA damage and cellular senescence." (PMID 24383451, 2014). "This suggests that elimination of TIGAR may be a strategy to radio-sensitize TrxR1-overexpressed gliomas." (PMID 36437984, 2022). "TIGAR improve the survival rate of glioma cells under hypoxia." (PMID 36437984, 2022). "TIGAR can improve the survival rate of glioma cells under hypoxia." (PMID 36437984, 2022). "TIGAR can also improve the survival rate of glioma cells under hypoxia." (PMID 36437984, 2022). "Moreover, IDH1 wild-type gliomas displayed a significantly increased expression of glycolytic enzyme genes (LDHA, HK2, PGAM2, PGK1, PKM, TIGAR) compared to IDH1-mutant gliomas as shown in heatmaps." (PMID 33493139, 2021). "In glioma cells, downregulation of TIGAR expression by siRNA results in radiosensitization." (PMID 34299056, 2021). "Antagonizing TIGAR may also facilitate glioma progression by maintaining an immunosuppressive milieu." (PMID 30823646, 2019). "However, in IR-exposed glioma cells, Trx1 nuclear translocation was notably diminished by TIGAR knockdown not only in pcDNA3.1 transfected cells but in TrxR1-overexpressing ones." (PMID 28338004, 2017). "Interestingly, TrxR1-overexpressing glioma cells are apparently re-radiosensitized by TIGAR silence." (PMID 28338004, 2017). "Moreover, TIGAR abrogated gliomas became necrosis after 20-Gy irradiation, suggesting a potentially radiosensitive effect on malignant gliomas." (PMID 28338004, 2017). "Furthermore, TIGAR interfering was performed to radiosensitize TrxR1-overexpressing glioma both in vitro and in vivo." (PMID 28338004, 2017). "Importantly, TrxR1-overexpressing U-87MG and T98G glioma cells were considerably re-radiosensitized by TIGAR silence." (PMID 28338004, 2017).
glioma (continued). "Our previous study demonstrated that TIGAR interfering was able to radiosensitize glioma cells." (PMID 28338004, 2017). "Besides, the radiosensitivity of glioma cells co-treated with TrxR1 overexpression and TIGAR knockdown was even higher than that of control cells, indicating an excellent radiosensitizing effect of TIGAR interfering." (PMID 28338004, 2017). "However, whether TrxR1-overexpressing glioma cells could be re-sensitized by TIGAR knockdown is still poorly understood." (PMID 28338004, 2017). "Importantly, TIGAR shRNA lentivirus transfection could not only radiosensitize U-87MG xenografts but dramatically enhanced the radiosensitivity of TrxR1-overexpressing gliomas." (PMID 28338004, 2017). "However, whether TrxR1-overexpressing glioma cells could be re-radiosensitized by TIGAR silence is still far from clear." (PMID 28338004, 2017). "In the glioma cell lines U87MG and T98G, an increase in TIGAR was observed following irradiation and suppression of irradiation-induced TIGAR by RNA interference reduced colony-forming capacities." (PMID 30823646, 2019). "Using glioma cell lines LNT-229 and T98G, we previously observed that the ectopic expression of TIGAR attenuated cell death induced by glucose and oxygen restriction, lowered ROS levels, and raised concentrations of reduced glutathione." (PMID 30823646, 2019). "Post-radiotherapy, TIGAR low-expression predicted significant longer survival time for animals suffering from TrxR1-overexpessing xenografts, which suggested that TIGAR abrogation might be a promising strategy for radiosensitizing TrxR1-overexpressing glial tumours." (PMID 28338004, 2017). "Conversely, under physiologic oxygen conditions (5% O2), TIGAR reduces Glu uptake and lactate levels, enhancing mitochondrial respiration and ATP production, as well as PPP activity, improving glioma cell survival through a more efficient energy production and ROS detoxification." (PMID 38786726, 2024). "Considering the hallmark of reprogrammed metabolic pathways in cancer cells, it is not surprised to find dysregulated TIGAR expression in various cancer types, including lung cancer, intestinal cancer, liver cancer, and glioma 22, 25-27." (PMID 31892967, 2020). "Western blot assays revealed that TIGAR abrogation alone was incapable of inhibiting the basal expression level of nuclear Trx1 in glioma cells with or without TrxR1 overexpression." (PMID 28338004, 2017). "Silencing TIGAR also enhanced the radiosensitivity of U87MC and glioma cells." (PMID 27884166, 2016). "However, it has been found that TIGAR has no impact on NF-κB activation in the neocarzinostatin-treated glioma cells." (PMID 38773142, 2024). "Importantly, TIGAR knockdown induced dramatic NADPH depletion in irradiated glioma cells no matter whether TrxR1 was overexpressed or not." (PMID 28338004, 2017).